CCL5 (C-C motif chemokine ligand 5)
Diseases named in the same sentence as CCL5 in open-access papers (continued):
Sharing a sentence is not in itself a finding about the gene and the disease.
Obesity (continued). "Serum levels of numerous obesity-linked chemokines promoting adipocyte proliferation (TIMP-1) and adipose macrophage infiltration (CXCL1, CXCL2, CXCL12, CCL3, and CCL5) were found to be significant predictors of in vivo hippocampal TSPO signals." (PMID 27578213, 2016). "However, the role of CCL5 in obesity-induced adipose tissue inflammation remains obscure." (PMID 36713454, 2022). "However, the respective contributions of tissue-derived and myeloid-derived CCL5 to the etiology of obesity-induced adipose tissue inflammation and insulin resistance, and the involvement of monocytic myeloid-derived suppressor cells (MDSCs), remain unclear." (PMID 36430701, 2022). "However, we also noted discordance between gene and protein expression of CCL2 and CCL5 in the adipose tissue which may be due to variability in the stabilities of their mRNAs and proteins in the adipose tissue in obesity." (PMID 31718015, 2019). "We now know that diseases that fall into the metabolic syndrome spectrum, such as T2DM and obesity, are associated with dysfunctional immunity and low low-grade inflammation, as shown by increased levels of proinflammatory cytokines such as TNF-α, IL-6, and chemotactic factors (e.g., CCL5 and CCL8)." (PMID 29765984, 2018). "This justified further interest in the potential role of CCL5 as a modulator of the activity of hypothalamic neurons regulating food intake and which could possibly promote the establishment and/or development of obesity." (PMID 28855891, 2017). "In addition to IL-6, recent studies suggest that CCL5 is another key player in obesity-related adipose tissue inflammation; gene expression of CCL5 in adipose tissue is increased in obese subjects, and CCL5 increases monocyte migration and macrophage survival in human adipose tissue." (PMID 24918199, 2014). "In obesity-induced type 2 diabetes, pro-inflammatory molecules like IL-1β, IL-6, CCL2, CCL5, and leptin play key roles in the accumulation of MDSCs in adipose tissue." (PMID 39518420, 2024). "This review provides an in-depth analysis of specific chemokines involved in the development of obesity, including C-C motif chemokine ligand 2 (CCL2), CCL3, CCL5, CCL7, C-X-C motif chemokine ligand 8 (CXCL8), CXCL9, CXCL10, CXCL14, and XCL1 (lymphotactin)." (PMID 39334887, 2024). "In obesity, the levels of inflammatory mediators increases, and the recruitment of immune cells through chemokine signalling pathways (including CCL2 and CCL5) contributes to the transition of inflammation into a chronic process." (PMID 39275140, 2024). "Patients under 65 years old showed a higher expression of TFRC (p = 0.002), CCL5 (p < 0.001) and IFI6 (p = 0.006), and those with obesity (BMI ≥ 30) presented higher expression of OAS1 (p = 0.008) and TGFB1 (p = 0.008)." (PMID 38731851, 2024). "The selective and more pronounced increase in CCL5 in the T2DM group with normal BMI, compared to subjects with varying degrees of obesity, was rather surprising." (PMID 39063997, 2024). "Obesity induces upregulated expression of chemokines such as MCP-1 (monocyte chemoattractant protein-1, CCL2) and CCL5 (C-C Motif Chemokine Ligand 5) in order to recruit M1 macrophages to adipose tissues." (PMID 36838843, 2023). "CCL2 and CCL5 have been reported to increase, particularly in the ATM fraction, with obesity, and are correlated with T cells in adipose tissue." (PMID 35052852, 2022). "However, the role of CCL5 in obesity-induced adipose inflammation remains unclear." (PMID 36713454, 2022). "CCL5 gene deletion significantly ameliorated HFD-induced inflammatory reactions in eWAT and protected against the development of obesity and insulin resistance." (PMID 36430701, 2022). "Activated stress pathways found in obesity drive the expression of chemokines like C-C motif chemokine ligand 2 (CCL2), CCL8, and CCL5, and chemokine receptors (e.g. CCR2 and CCR5), which help recruit macrophages to the dysfunctional tissue." (PMID 32133436, 2019).
Obesity (continued). "Obesity is a state of chronic low-grade systemic inflammation which induces the production of several chemokines including CCL2, CCL5, and CXCL5." (PMID 31817755, 2019). "Plasma CCL-5 (also called regulated on activation, normal T cell expressed and secreted or RANTES), and CRP are typical markers of systemic inflammation while the increased triglyceride levels are clinical indicator of obesity." (PMID 26312071, 2015). "CCL5 gene knockout significantly ameliorated high-fat diet (HFD)-induced inflammatory reactions in epididymal white adipose tissue and protected against the development of IR and obesity in mice fed HFD compared to control mice." (PMID 40423250, 2025). "With this background, we intend to study the relationship between pro-inflammatory chemokines CCL1, CCL2, CCL4, and CCL5 and the etiopathogenesis of T2DM in subjects with varying levels of obesity, BMI, and HbA1c in a patient cohort from the Asir region of Saudia Arabia." (PMID 39063997, 2024). "Circulating levels of the intestinal inflammatory factors CCL5 and IL-6 as well as the IL-18/IL-18BP ratio were increased (P < 0.05) in patients with obesity with and without T2D being also significantly associated with endotoxin levels." (PMID 38315242, 2024). "Using a T2DM and a control cohort from the Asir region of Saudia Arabia, we looked into the association between the pro-inflammatory chemokines CCL1, CCL2, CCL4, and CCL5 and the etiopathogenesis of T2DM in subjects with different degrees of obesity, BMI, and HbA1c." (PMID 39063997, 2024). "Overall, systemic CCL5, GDF15, and IGFBP6 levels declined following 12 months of anti-obesity therapy and weight loss, irrespective of a conservative or bariatric approach." (PMID 36430499, 2022). "Our recent study has demonstrated that obesity-induced augmentation of CCL5/CCR5 signaling suppressed adaptive thermogenesis by inhibiting AMPK-mediated lipolysis and oxidative metabolism in BAT to deteriorate the development of obesity." (PMID 34948325, 2021). "The chemokine CCL5 (also known as regulated on activation, normal T cell expressed and secreted [RANTES]) is upregulated in VAT in obesity and may account for the recruitment of T cells into obese VAT." (PMID 30459770, 2018). "Our observation that T2DM subjects with varying levels of obesity (Groups B to D) showed significantly lower CCL5 levels, irrespective of gender, as compared to T2DM subjects with normal body weight (Group A), is somewhat bewildering and we do not have any concrete explanation for this phenomenon." (PMID 39063997, 2024). "Based on studies in mouse models, lymphocyte infiltration in adipose tissue might occur in a chronological sequence with T lymphocytes being recruited during early obesity-induced inflammation by chemokines like RANTES, a T-cell specific chemokine also known as CCL5." (PMID 24106481, 2013). "Also, the high number of chemokines induced (most of which have redundant properties) supports the fact that leukocyte adipose tissue infiltration observed during obesity is not related to one or two proteins such as CCL2 or CCL5." (PMID 23824685, 2013). "However, it is not known whether the CCL5/CCR5 axis is involved in obesity-driven MDSCs and insulin resistance." (PMID 36430701, 2022). "Our current data suggest that boosting intratumoral anti-tumor effector signals, such as CCL5, or blocking pro-inflammatory signals such as GM-CSF and IL-6, could serve as therapeutic options in combination with ICB, particularly in patients with combined obesity and RCC." (PMID 34064933, 2021). "Notably, significant elevations in IL-2 expression in the AT together with that of other inflammatory mediators (IL-8, IL-12A, CCL5, CCL19, CCR2 and CCR5 and TLRs) in obesity suggests that these factors may contribute cooperatively for insulin resistance induction in this population." (PMID 33004937, 2020).
prostate carcinoma (86 papers, 2008 to 2026). A carcinoma that arises from epithelial cells of the prostate gland. "In prostate cancer (PCa), ERα positivity inhibits CCL5 expression in cancer-associated fibroblasts (CAFs), leading to reduced macrophage infiltration, migration of M2 macrophages, and inhibition of prostate cancer invasion." (PMID 40959082, 2025). "It was also previously established that CCL5 rs2107538 was a risk factor for prostate cancer, hepatocellular carcinoma, oral cancer, and papillary thyroid cancer." (PMID 38001676, 2023). "For example; tumor-associated macrophage (TAM)-derived CCL5 or the addition of CCL5 promotes prostate cancer metastasis and drug resistance through a STAT3-dependent epithelial-mesenchymal transition process and upregulation of the transcription factor Nanog." (PMID 36387070, 2022). "High expressions of CCL5 are associated with high Gleason grade and poor prognosis in prostate cancer patients." (PMID 34745140, 2021). "Altogether, CCL5 was mainly secreted by TAMs, and its expression was elevated in prostate cancer and associated with metastasis." (PMID 32300100, 2020). "More importantly, elevated CCL5 expression was positively associated with high Gleason grade, poor prognosis, metastasis, and increased PCSCs activity in prostate cancer patients." (PMID 32300100, 2020). "CCL5 is also secreted by prostate cancer-associated fibroblasts and recruited macrophages into the prostate cancer microenvironment." (PMID 30871130, 2019). "In the current study, possession of the CCL5 rs3817655 A or CCL5 rs2107538 A loci was linked with a protective effect in relation to prostate cancer risk among all men of African descent from the U.S. and Jamaica combined." (PMID 23168091, 2012). "Uncovering the underlying mechanism for CCL5-induced STAT3 activation might provide potential therapeutic targets for prostate cancer." (PMID 32300100, 2020). "Functionally, CCL5 enhances PCa cell invasion and supports prostate cancer stem cell self-renewal in vivo." (PMID 41228234, 2025). "In a cell culture setup, the CCR1/CCL5 interaction supports the invasion of taxane-resistant prostate cancer cells through the activation of ERK and Rac signaling pathways." (PMID 40076892, 2025). "CCL5 produced by TAMs in prostate cancer enhances resistance to PTX and DOX via the STAT3/Nanog signaling pathway." (PMID 39199574, 2024). "In prostate cancer, tumor-associated macrophages secrete pro-inflammatory cytokines such as CCL2 and CCL5, thus enhancing the migratory ability of prostate cancer cells to other parts of the body, especially the bone." (PMID 38398019, 2024). "Applying pressure to osteocytes induced prostate cancer growth and invasion via the upregulation of CCL5 and MMP." (PMID 39459070, 2024). "TAM-derived CCL5 promotes self-renewal of prostate cancer stem cells (PCSCs) and prostate cancer metastasis via activation of β-catenin/STAT3 signaling." (PMID 39199574, 2024). "Similar to our results, in prostate cancer, CCL5 can enhance cell migration and invasion by promoting EMT." (PMID 39227943, 2024). "Exerting pressure on osteocytes in a mouse model induced prostate cancer growth and invasion, and mechanistic analysis further revealed that the process was mediated by the upregulation of CCL5 and matrix metalloproteinases in the cells." (PMID 39459070, 2024). "In a study by Messex and Liou, CCL5 was added to a culture of prostate cancer cells, and thus, increased migratory and invasive abilities were observed." (PMID 38398019, 2024). "Silencing of CCL5 in TAMs inhibits bone metastasis and self‐renewal of PCSCs in vivo and therefore TAMs/CCL5 can be a novel target in predicting prognosis of prostate cancer and inhibiting metastasis." (PMID 38703051, 2024). "Treating prostate cancer cells with exogenous recombinant CCL5 resulted in a lower sensitivity of prostate cancer cells in response to docetaxel." (PMID 36836690, 2023).
prostate carcinoma (continued). "TAMs are capable of enhancing migration of prostate cancer cells via their secretion of various cytokines such as CCL5 and CCL2 while simultaneous activation of enzymes including TRAP5b grants access to new areas of the body, e.g., bones." (PMID 36836690, 2023). "While STAT3 pathway activation led to upregulation of CCL2 and induction of EMT in prostate cancer cells, CCL5 was also found to activate STAT3 signaling." (PMID 36836690, 2023). "CCL5 was identified as a responsible cytokine secreted by CD4+ T cells for this high chemoresistance of prostate cancer cells." (PMID 36836690, 2023). "In vivo, PC-3 xenografted SCID mice injected with THP-1-derived TAMs showed a significant increase in bone metastasis while CCL5 knockdown blocked bone metastasis from prostate cancer, suggesting CCL5 as a major contributor to prostate cancer migration." (PMID 36836690, 2023). "In vitro studies using the exogenous addition of CCL5 to culture human prostate cancer cell lines DU145 and PC3 showed elevated migratory and invasive abilities of cancer cells." (PMID 36836690, 2023). "Spatial transcriptomic analysis of prostate cancer confirmed colocalization of the CD16neg NK cell signature and CCL5 transcripts." (PMID 34936871, 2021). "In response to prostate cancer cell growth-induced pressure, osteocytes produce CCL5, which promotes tumor proliferation in the bone." (PMID 34745140, 2021). "Studies have also shown that CCL5 can promote the growth of colorectal cancer and prostate cancer, which can be inhibited by TAK‐779, a CCR5 antagonist." (PMID 33943003, 2021). "The relationship between CCL5 expression and breast, colon, and prostate cancer is well established, and as a result, CCL5 and CCR5 have emerged as therapeutic targets for restricting metastatic cancer." (PMID 34399621, 2021). "QPCR screening validated STAT3 as the most significant response gene in prostate cancer cells following CCL5 treatment." (PMID 32300100, 2020). "Elisa assay further convinced that TAMs exhibited a significantly increased secretion of CCL5 than the immature macrophages (M0) or prostate cancer cells." (PMID 32300100, 2020). "CCL5 secreted by TAMs increases prostate cancer stem cell expansion and tumor cell invasion via activating β-catenin/STAT3 signaling." (PMID 32630699, 2020). "To confirm the key role of STAT3 in CCL5-induced promotion effect on prostate cancer, we further investigated the combined effect of CCL5 and STAT3 inhibitor." (PMID 32300100, 2020). "Elisa assay further indicated that the blood samples of prostate cancer patients exhibited elevated expression of CCL5 when compared with that of healthy male participants." (PMID 32300100, 2020). "The tyrosine kinase inhibitor gefitinib inhibits epidermal growth factor receptor (EGFR) activation on MSCs by conditioned medium from PC3 prostate cancer cells (bone metastasis of prostate cancer), leading to decreased secretion of CCL5." (PMID 32630699, 2020). "In order to validate the metastasis promotion effects of CCL5, we further investigated the effect of recombinant human CCL5 protein on prostate cancer metastasis using human prostate cancer cell lines DU145 and PC3." (PMID 32300100, 2020). "More importantly, high CCL5 expression in prostate cancer patients usually predicated poor overall survival (p = 0.05) and poor progression-free survival (p = 0.0066)." (PMID 32300100, 2020). "Overall, this study not only revealed the underlying mechanisms by which TAMs promoted PCSCs but also uncovered TAMs/CCL5 as a novel target in predicting prostate cancer prognosis and inhibiting prostate cancer metastasis." (PMID 32300100, 2020). "We analyzed the mRNA expression differences of a panel of metastasis and stemness-related genes in prostate cancer cells after CCL5 treatment." (PMID 32300100, 2020). "Prostate cancer patients with higher Gleason grade exhibited an increased CCL5 accumulation in the blood." (PMID 32300100, 2020).
prostate carcinoma (continued). "More significantly, CCL5 knockdown in TAMs by genetic approaches suppressed prostate cancer growth, bone metastasis and PCSCs activity in vivo." (PMID 32300100, 2020). "It was found that prostate cancer patients with high Gleason grade (GS > 7) exhibited increased CCL5 expression (p < 0.05)." (PMID 32300100, 2020). "Altogether, these results validated that STAT3 acted as the primary response gene accounting for the promotion effect of CCL5 on prostate cancer cells." (PMID 32300100, 2020). "Firstly, the prognostic value of CCL5 for prostate cancer patients was determined by analyzing the expression difference of CCL5 in prostate cancer specimens and nonmalignant specimens." (PMID 32300100, 2020). "Next, the mechanism by which CCL5 promoted the invasion and the PCSCs subpopulation of prostate cancer cells was explored." (PMID 32300100, 2020). "The interaction of prostate cancer cells with MSCs increases CCL5 secretion in both cell types and conditioned medium from prostate cancer cells increases CCL5 secretion by MSCs." (PMID 32630699, 2020). "THP1-derived TAMs co-injection not only significantly accelerated PC-3-Luc xenografts growth but also increased the bone metastasis of prostate cancer xenografts, whereas CCL5 knockdown in THP1-derived TAMs significantly abrogated that." (PMID 32300100, 2020). "Of note, multiple genes hitherto known to be associated with prostate cancer progression were observed in the top list of upregulated entities including but not limited to MYBL2, ESM1, PBK, and UBE2C in PC3, and MMP1, CCL5, and STC1 in DU145." (PMID 31493351, 2019). "Upregulation of CCL5 has previously been reported to increase the aggressive potential of breast cancer cells and the invasiveness of prostate cancer cells." (PMID 30871130, 2019). "Depletion of PKD2 and PKD3 in prostate cancer cells significantly decreased binding of p65, c-Jun and c-Fos to the scf, ccl5, and ccl11 promoter." (PMID 30841931, 2019). "To further study the effect of CCL5 on prostate cancer cells and AR, we treated C4–2 or CWR22Rv1 with CCL5 respectively." (PMID 30200999, 2018). "We use CPRC prostate cancer model and demonstrate that endothelial cells secrete large amount of CCL5 and induces autophagy by suppressing AR expression in prostate cancer cell lines." (PMID 30200999, 2018). "Increased surrounding infiltrating bone marrow mesenchymal stem cells directly suppress AR expression through CCL5/HIF2α pathway and CCL5 from the bone microenvironment has been shown to promote the growth of prostate cancer bone metastases." (PMID 30200999, 2018). "In prostate cancer, CCL5 promotes invasion by increasing the secretion of both MMP-2 and -9 and by activating extracellular signal–regulated kinases (ERK) and Rac signaling." (PMID 29772686, 2018). "It inhibited HIV infection and CCL5-induced proliferation and invasion of prostate cancer cells (PCa)." (PMID 29772686, 2018). "Blocking the interaction between CCL5 and prostate cancer cells in context of endothelial cells can attenuate this effect." (PMID 30200999, 2018). "In humans, both CXCL2 and CCL5 have been suggested to promote prostate cancer development and indeed increased CCL5 levels were observed in human prostate cancer." (PMID 29212195, 2017). "It has also been reported that chemokine ligand 5 (CCL5) secreted by bone marrow-derived MSCs increases prostate cancer stem cell population and metastatic ability." (PMID 28750689, 2017). "Here, we found the CCL5 secreted from BM-MSCs suppressed androgen receptor (AR) signals via enhancing the expression of hypoxia inducible factor 2α (HIF2α) in prostate cancer (PCa) cells." (PMID 26342197, 2015). "The CCL5/CCR5 axis is involved also in prostate cancer (PCa) progression: both are expressed in human prostate cancer (PCa) cell lines, primary cultures of prostatic adenocarcinoma cells, and PCa tissues." (PMID 24523569, 2014).